TFPI (tissue factor pathway inhibitor)
Diseases named in the same sentence as TFPI in open-access papers (continued):
Sharing a sentence is not in itself a finding about the gene and the disease.
prostate carcinoma (3 papers, 2010 to 2021). A carcinoma that arises from epithelial cells of the prostate gland. "Five other PS up-regulated genes (MERTK13, APLP2, CLDN 3, DUSP6 and TFPI) have been found to be overexpressed in prostate cancer and many other tumor types, but their role in tumor biology is less understood." (PMID 20500816, 2010). "miR-500 inhibition could suppress the proliferation and invasion of prostate cancer cells and tumorigenicity in vivo, while TFPI knockdown reversed these effects." (PMID 34115774, 2021).
thrombotic disorders (3 papers, 2017 to 2021). "Much studies demonstrated that lower plasma TFPI-1 levels were associated in individuals with venous and arterial thrombotic disease." (PMID 28246607, 2017). "Lower TFPI-1 levels were associated with a lot of thrombotic disease." (PMID 28246607, 2017). "TFPI is involved in coagulation initiation, and therefore it is conceivable that platelet TFPI modulates bleeding as well as thrombotic disorders." (PMID 28158181, 2017). "TF is responsible for triggering the clotting cascade in a variety of thrombotic disorders, thus using anticoagulants, such as tissue factor pathway inhibitor (TFPI) or antithrombin that may be useful in the treatment of ALI and ARDS." (PMID 34804364, 2021).
acromegaly (2 papers, 2019 to 2024). Acromegaly is an acquired disorder related to excessive production of growth hormone (GH) and characterized by progressive somatic disfigurement (mainly involving the face and extremities) and systemic manifestations. "In fact, some studies found increased levels of fibrinogen and plasminogen activator inhinibitor-1 (PAI-1), and decreased levels of tissue plasminogen activator (t-PA) and tissue factor pathway inhibitor (TFPI) in acromegaly." (PMID 31396153, 2019).
acute kidney injury (2 papers, 2024). Sudden and sustained deterioration of the kidney function characterized by decreased glomerular filtration rate, increased serum creatinine or oliguria. "High TFPI levels were associated with acute kidney injury, liver dysfunction, DIC and disease severity." (PMID 38914630, 2024).
acute respiratory distress syndrome (2 papers, 2015). Progressive and life-threatening pulmonary distress in the absence of an underlying pulmonary condition, usually following major trauma or surgery. "Notably, TFPI in pulmonary edema fluid in patients with the acute respiratory distress syndrome (ARDS) has been shown to be truncated and inactive." (PMID 25992779, 2015).
breast tumor (2 papers, 2014 to 2015). "As expected, the total TFPI (α + β), TFPIα and TFPIβ mRNA expression levels in breast tumors were highly correlated (r = 0.82 to 0.91, P <0.001), and did also correlate significantly to TF expression (r = 0.37-0.50, P <0.001)." (PMID 25882602, 2015). "First, we investigated the clinical relevance of TFPI or TF mRNA expression in breast tumors and TFPI or TF plasma concentrations." (PMID 25882602, 2015). "TFPI or TF mRNA expression in breast tumors and plasma concentrations were then compared between the five molecular tumor subtypes (respectively)." (PMID 25882602, 2015). "Further, we aimed to explore whether the TFPI or the TF SNPs had any transcriptional or translational regulatory effects on the TFPI or TF mRNA expression in the breast tumors, or on the protein levels in plasma, respectively." (PMID 25882602, 2015).
cervical cancer (2 papers, 2020 to 2022). A primary or metastatic malignant neoplasm involving the cervix. "Three genes (COPE, RAB3B, and TFPI) in the network were significantly associated with overall survival (P < 0.05), which indicated that these genes could act as prognostic biomarkers for patients with cervical cancer." (PMID 33330502, 2020). "Analysis of a TCGA dataset revealed that a total of 3 target genes (COPE, RAB3B, and TFPI) in the regulatory network were correlated to survival curves with clinically significant outcomes in cervical cancer." (PMID 33330502, 2020).
dengue (2 papers, 2021 to 2025). "In our study, higher levels of TFPI and lower levels of TF were found in dengue patients than in healthy controls, which could be linked to the higher frequency of DENV-4 infected patients." (PMID 34578370, 2021). "Among the coagulation mediators analyzed, TF and TFPI together with IL-6 formed the second pattern identified in the dengue patients through PCA analysis." (PMID 34578370, 2021). "In addition, our study found a positive association between APRI values and the levels of pro-inflammatory cytokines, chemokines and coagulation mediators (IL-6, IL-18, CXCL10/IP-10 and TFPI) in dengue patients." (PMID 34578370, 2021). "Plasminogen was increased in the pre-COVID-19 Dengue group compared to healthy controls, while TFPI levels did not differentiate the groups." (PMID 41305453, 2025).
glioma (2 papers, 2021 to 2022). A benign or malignant brain and spinal cord tumor that arises from glial cells (astrocytes, oligodendrocytes, ependymal cells). "In contrast, expression of TFPI antigens associated with vascular endothelial cells was pronounced in glial cells of lower-grade malignancy and in areas of vascular hyperplasia in gliomas of higher-grade malignancy." (PMID 33947134, 2021). "A strong expression of TFPI-2, PS, TM, PAI-1 was observed in lower-grade gliomas, while an intensive color immunohistochemical (IHC) reaction for the presence of TFPI antigens was detected in higher-grade gliomas." (PMID 33947134, 2021). "The extent of the expression of TFPI connected with tumor cells was proportional to the grade of malignancy, i.e., the strongest expression was characteristic of glioma cells of the highest-grade malignancy." (PMID 33947134, 2021). "In terms of these considerations, the role of the tissue factor-dependent blood coagulation pathway TFPI and TFPI-2 inhibitors in the control of glial tumor growth and in the coagulation process in loco is interesting." (PMID 33947134, 2021). "In turn, the high expression of TFPI in vascular endothelial cells of gliomas, depending on the degree of malignancy, may indicate the role of this protein in maintaining hemostasis." (PMID 33947134, 2021). "In the present study, we report elevated expression of TFPI in higher-grade gliomas." (PMID 33947134, 2021).
hepatocellular carcinoma (2 papers, 2021 to 2024). A malignant tumor that arises from hepatocytes. "We found the co-expression of TFPI and GPC3 on the surface of CLL cells and co-IP confirmed the binding between the two proteins, which is consistent with previous studies on the hepatocellular carcinoma cell line HepG233 and hematopoietic stem cells." (PMID 33664415, 2021).
influenza (2 papers, 2021 to 2025). An acute viral infection of the respiratory tract, occurring in isolated cases, in epidemics, or in pandemics; it is caused by serologically different strains of viruses (influenzaviruses) designated A, B, and C, has a 3-day incubation period, and usually lasts for 3 to 10 days. "TFPI correlated negatively with TLR3 and TLR7 in COVID19 but positively in influenza." (PMID 40825056, 2025).
pneumonia (2 papers, 2013 to 2015). An acute, acute and chronic, or chronic inflammation focally or diffusely affecting the lung parenchyma, caused by an infection in one or both of the lungs (by bacteria, viruses, fungi, or mycoplasma.). "Thirty minutes before and every 6 hours after intratracheal instillation of S. pneumonia causing pneumonia, rats were subjected to local treatment with rh-TFPI or placebo, and sacrificed after 42 hours." (PMID 25992779, 2015). "In conclusion, the TF-mediated procoagulant environment within the lung compartment during pneumonia provides a rationale for local treatment with rh-TFPI." (PMID 25992779, 2015). "The present study shows that local administration of rh-TFPI by nebulization is feasible and safe in a well-established rat model of S. pneumoniae pneumonia." (PMID 25992779, 2015). "Systemic treatment with rh-TFPI is known to reduce activation of coagulation in both pre-clinical and clinical pneumonia studies." (PMID 25992779, 2015). "Together, these data confirm the efficacy of nebulized rh-TFPI to attenuate pulmonary coagulopathy in pneumonia and suggest that local administration of rh-TFPI does not pose a risk of systemic hemorrhage." (PMID 25992779, 2015). "TFPI was found to be in a mainly truncated and inactive form in lavage fluid of patients with ARDS, and TFPI activity was reduced in patients with pneumonia, suggesting rh-TFPI may be of therapeutic value in this setting." (PMID 25992779, 2015). "Therefore, we aimed to examine feasibility and safety of nebulization of recombinant human tissue factor pathway inhibitor (rh-TFPI) in a well-established rat model of Streptococcus (S. ) pneumoniae pneumonia." (PMID 25992779, 2015). "We conclude that nebulization of rh-TFPI seems feasible and safe; local anticoagulant treatment with rh-TFPI attenuates pulmonary coagulation, while not affecting systemic coagulation in a rat model of S. pneumoniae pneumonia." (PMID 25992779, 2015). "Nebulization of rh-TFPI did not result in local bleedings, neither in unchallenged rats, nor in rats with pneumonia." (PMID 25992779, 2015). "Although systemic dissemination has been suggested as a potential drawback of anticoagulant treatment in pneumonia, local treatment with rh-TFPI did not influence bacterial counts in the lung or systemic compartment." (PMID 25992779, 2015). "Unlike levels of PAI-1, the TFPI levels in plasma seem not to vary in response to e.g., pneumonia, and it was concluded that TFPI does not behave as an acute-phase reactant." (PMID 23898467, 2013).
pulmonary hypertension (2 papers, 2013 to 2023). Increased pressure within the pulmonary circulation due to lung or heart disorder. "A mouse overexpressing tissue factor pathway inhibitor (TFPI) was found to have reduced pulmonary hypertension when exposed to hypoxia." (PMID 23785394, 2013).
septic shock (2 papers, 2024). Shock caused by infection; frequently caused by gram negative bacteria, although some cases have been caused by other bacteria, viruses, fungi, and protozoa; characterized by fever, chills, tachycardia, tachypnea, and hypotension. "Adjunctive TPE in septic shock is associated with a significant removal of both TF and TFPI, which may contribute to the early hemodynamic improvement observed in septic shock patients receiving TPE." (PMID 39478586, 2024). "Patients with septic shock had 1.6-fold higher levels of TF and 2.9-fold higher levels of TFPI than HC." (PMID 38914630, 2024). "Thus, the aim of this study was to investigate whether the ratio of TF/TFPI in blood is associated with organ dysfunctions, DIC and outcome in patients with septic shock and whether the TF/TFPI ratio differs between the subgroups of patients with INR < 1.2 and those with an INR ≥ 1.2." (PMID 38914630, 2024). "In order to further investigate the predominant increase in TFPI compared to TF in patients with septic shock and the tendency to a lower TF/TFPI ratio in non-survivors, septic shock patients were stratified according to ICU-survival and peak levels of TF pathway parameters were compared." (PMID 38914630, 2024).
thrombotic thrombocytopenic purpura (2 papers, 2012 to 2021). "Plasma TFPI levels were significantly decreased in patients with thrombotic thrombocytopenic purpura (TTP) compared with those in healthy volunteers." (PMID 34501736, 2021).
abetalipoproteinemia (1 paper, 2017). "Therefore, total TFPI and LDL covariate in plasma and as a result patients with abetalipoproteinemia, lacking apolipoprotein B, an important component of LDL, have very low levels of both LDL and total TFPI." (PMID 28158181, 2017).
allergic asthma (1 paper, 2022). A asthma with a basis in a pathological type I hypersensitivity reaction. "TCONS_00004989 also competitively inhibits the expression of the tissue factor pathway inhibitor (TFPI) gene through trans regulation, which is considered to be a molecular marker of elevated chronic bronchial inflammation and remodeling in allergic asthma." (PMID 36463267, 2022).
Arthritis (1 paper, 2025). Inflammation of a joint. "Given that TFPI, as a fibrinolytic factor, can inhibit fibrin formation and alleviate arthritis symptoms, increasing TFPI expression may positively contribute to the improvement of knee arthritis." (PMID 40429617, 2025). "Through the positive feedback mechanism of heparanase, the synergistic upregulation of TFPI expression can restore hemostatic balance and enhance osteoblast activity, thereby improving bone tissue repair capability, which may facilitate arthritis repair." (PMID 40429617, 2025). "Additionally, another human control experiment revealed that persistent fibrin deposition induces arthritis and that TFPI levels in synovial fluid are significantly lower than those in healthy individuals." (PMID 40429617, 2025).
Behçet's disease (1 paper, 2022). "We report a case of Behçet's disease (BD) with a newly identified tissue factor pathway inhibitor (TFPI) gene mutation." (PMID 35514752, 2022).
brain ischemia (1 paper, 2023). Diminished or absent blood supply to the brain caused by obstruction (thrombosis or embolism) of an artery resulting in neurologic damage. "The lack of TFPI K1 domain also leads to elevated thrombin-antithrombin (TAT) levels, aberrant renal fibrin deposition, extensive brain ischemia and infarction, and an increased risk of the TF-induced pulmonary thromboembolism." (PMID 37238908, 2023).
chronic cholecystitis (1 paper, 2014). "We characterised a tissue factor (TF) and tissue factor pathway inhibitor (TFPI) expression in relation to severity of inflammatory infiltration of the gallbladder mucosa in a chronic cholecystitis." (PMID 24716194, 2014). "The most capillary endothelial cells in the cholecystitis group presented weak immunoreactivity for TFPI." (PMID 24716194, 2014). "The phenotype expression of the mucosal TF and TFPI differed significantly between the cholecystitis and the control group." (PMID 24716194, 2014). "The expression of TF and TFPI differed significantly between the cholecystitis and the control group." (PMID 24716194, 2014). "Most capillary endothelial cells of the cholecystitis group presented weak expression for TFPI." (PMID 24716194, 2014).
chronic kidney disease (1 paper, 2019). Impairment of the renal function secondary to chronic kidney damage persisting for three or more months. "Urine samples from 113 biopsy-proven LN patients (89 active LN and 24 inactive LN), 45 chronic kidney disease patients, and 41 healthy controls were examined for d-dimer, plasmin, TF, and TFPI levels by ELISA." (PMID 31319876, 2019).
coronary stenosis (1 paper, 2011). Narrowing of the coronary artery lumen diameter. "There is only one study where f-TFPI plasma levels were investigated in patients with atypical chest pain and non significant coronary stenosis, and were found to be similar to patients with stable angina." (PMID 21619612, 2011).
crescentic glomerulonephritis (1 paper, 2019). A histopathologic term for a pattern of diseases characterized by extensive crescent formation in the glomeruli; patients present clinically with rapid deterioration of renal function, and possible progression to end-stage renal failure within weeks or months. "TFPI was also found to be induced to inhibit TF activity and reduce fibrin deposition in the chronic stages of crescentic glomerulonephritis (GN)." (PMID 31319876, 2019).
Encephalopathy (1 paper, 2020). Encephalopathy is a term that means brain disease, damage, or malfunction. "Abnormal functions of this MVE lead to abnormal haemostasis that may be involved in both encephalopathy and acute respiratory distress, a novel therapy to alleviate this failure from its molecular origins consists in the use of tissue factor pathway inhibitor (TFPI)." (PMID 32982776, 2020).
endotoxemia (1 paper, 2024). "For example, in a mouse model of endotoxemia, the observed decline in lung-associated TFPI activity was prevented in plasminogen knockout mice." (PMID 39624584, 2024).
esophageal cancer (1 paper, 2017). A primary or metastatic malignant neoplasm involving the esophagus. "A similar gene TFPI2 was reported to be frequently methylated in esophageal cancer with a progression tendency, which indicated that TFPI methylation might also play roles in esophageal cancer." (PMID 28393072, 2017).
gastric cancer (1 paper, 2025). A primary or metastatic malignant neoplasm involving the stomach. "The m6A reader protein YTHDF2 mediates the m6A modification of ONECUT2 mRNA, thereby activating TFPI transcription, leading to stemness in gastric cancer and resistance to oxaliplatin, providing a new treatment target to tackle gastric cancer that is resistant to oxaliplatin." (PMID 41584846, 2025).
glaucoma (1 paper, 2026). Increased pressure in the eyeball due to obstruction of the outflow of aqueous humor. "This study maps putative causal POAG proteins to conventional outflow pathway cells, highlighting SEL1L as a novel target for TM homeostasis and TFPI for drug repurposing, thereby providing data-driven hypotheses to facilitate precision glaucoma therapeutics." (PMID 42278218, 2026).
gram-negative bacterial infections (1 paper, 2024). Infections caused by bacteria that show up as pink (negative) when treated by the gram-staining method. "Several reports have demonstrated that TFPI can be used in the treatment of Gram-negative bacterial infections, suggesting a therapeutic strategy targeting the coagulation pathway, and nebulized or injected recombinant human TFPI has been reported to mitigate both pulmonary and systemic coagulation." (PMID 38664775, 2024).
head and neck carcinoma (1 paper, 2014). A carcinoma that arises from the head and neck region. "Of 138 genes identified as being associated with SF2, only 2 (1.4%) were congruent between the cervix and head and neck carcinoma cell lines (MGST1 and TFPI), and these did not partition the published NCI-60 cell lines based on SF2." (PMID 24466029, 2014).
hemophilia C (1 paper, 2024). "Whether anti-TFPI antibody should be used in patients with hemophilia C is debated largely because of the infrequent need for replacement products; however, their availability is important and may also play a role in the development of factor XI inhibitors for a variety of clinical indications." (PMID 38662114, 2024).
hemorrhage (1 paper, 2024). Loss of blood from the vascular compartment to the exterior or into nonvascular body space as a result of rupture or severance of the blood vessels. "Inhibition of TFPI may be especially suitable to therapy polycythemia with complication of hemorrhage." (PMID 38729948, 2024).
hypothyroidism (1 paper, 2012). Abnormally low levels of thyroid hormone. "Therefore, in a case-control study, we aimed to investigate the profile of coagulation/fibrinolytic and vascular endothelial cell function parameters including PAI, TAFI, TM, TFPI, and tPA in children with hypothyroidism." (PMID 22985614, 2012). "Up to date, most of the studies investigating the effect of hypothyroidism on coagulation factors such as TAFI, TM, PAI, tPA, and TFPI were conducted in adult patients." (PMID 22985614, 2012).
invasive breast carcinoma (1 paper, 2011). A carcinoma that infiltrates the breast parenchyma. "The effects of downregulation of TFPI were investigated in the two basal-like invasive breast carcinoma cell types Sum102 and MDA-MB-231." (PMID 21849050, 2011).